SIRT1 (sirtuin 1)
Diseases named in the same sentence as SIRT1 in open-access papers (continued):
Sharing a sentence is not in itself a finding about the gene and the disease.
chondrosarcoma (continued). "Transfection of cells with SIRT1 siRNA significantly reduced the increased cleavage of caspase-3 protein and caspase-3 activity in resveratrol-treated chondrosarcoma cells." (PMID 28600541, 2017). "Furthermore, we also found that SIRT1 effectively enhanced the metastasis by inducing epithelial-mesenchymal transition (EMT) in chondrosarcoma cells." (PMID 28112277, 2017). "Our results demonstrated that the expression of SIRT1 in chondrosarcoma cells could effectively regulate the metastatic plasticity of the cells by inducing epithelial-mesenchymal transition." (PMID 28112277, 2017). "Therefore, we tried to evaluate the therapeutic effects of resveratrol via SIRT1 activation on chondrosarcoma cell growth and tumor progression using an in vitro cell culture model and an in vivo xenograft mouse model." (PMID 28600541, 2017). "Taken together, these results indicated that SIRT1 might regulate the metastatic plasticity of chondrosarcoma cells by inducing EMT." (PMID 28112277, 2017). "Besides that, the result from the nude mice confirmed the effect of SIRT1 on metastasis of chondrosarcoma cells." (PMID 28112277, 2017). "Furthermore, we also found that SIRT1 effectively enhanced the metastasis by inducing EMT in chondrosarcoma cells." (PMID 28112277, 2017). "We first examined SIRT1 expression levels in clinical pelvis chondrosarcoma specimens." (PMID 28112277, 2017). "Immunohistochemical staining results showed that SIRT1 was overexpressed in pelvis chondrosarcoma." (PMID 28112277, 2017). "In conclusion, our results indicate that SIRT1 may promote the metastasis of chondrosarcoma cells by inducing EMT and can be a potential molecular target for chondrosarcoma therapy." (PMID 28112277, 2017). "On one hand, these results suggested that SIRT1 expression could effectively control the EMT level of chondrosarcoma cells." (PMID 28112277, 2017). "However, the role of SIRT1 and the detailed effects and mechanisms of resveratrol on chondrosarcoma are still needed to be clarified." (PMID 28600541, 2017). "SIRT1 overexpression was observed in 25 of 34 (73.5%) pelvis chondrosarcoma specimens." (PMID 28112277, 2017). "In this study, we demonstrated that up and down-regulation of SIRT1 expression could significantly lead to the change of invasive and metastatic potential in chondrosarcoma cell line." (PMID 28112277, 2017). "Besides that we also found the correlation between SIRT1 expression and the progression and prognosis of chondrosarcoma patients." (PMID 28112277, 2017). "Besides, the result from the nude mice confirmed the effect of SIRT1 on metastasis of chondrosarcoma." (PMID 28112277, 2017). "We next investigated whether SIRT1 activation by resveratrol affected NF-κB signaling in human chondrosarcoma cells." (PMID 28600541, 2017). "In this study, we demonstrated that up and down-regulation of SIRT1 expression could significantly change the invasive and metastatic potential in chondrosarcoma cell line." (PMID 28112277, 2017). "Taken together, these results indicate that SIRT1 may promote the metastasis of chondrosarcoma by inducing EMT and can be a potential molecular target for chondrosarcoma therapy." (PMID 28112277, 2017). "Then we explored the effect of SIRT1 on the chondrosarcoma cells metastasis in vivo." (PMID 28112277, 2017). "However, the effect of SIRT1 on the metastasis of chondrosarcoma cells is still unknown." (PMID 28112277, 2017). "Inhibition the expression of SIRT1 could block the incidence of metastasis and EMT in chondrosarcoma cells." (PMID 28112277, 2017). "Inhibition the expression of SIRT1 could inhibit the incidence of metastasis and EMT in chondrosarcoma cells." (PMID 28112277, 2017). "There is no report about the role of SIRT1 in the human chondrosarcoma cells." (PMID 28600541, 2017).
chondrosarcoma (continued). "In addition, patients with pelvis chondrosarcoma in the negative SIRT1 expression group showed a favorable survival outcome (P = 0.043), with mean survival times of 53.8 months, respectively compared with those of the positive expression group survival times of 37.7 months." (PMID 28112277, 2017).
chronic pancreatitis (5 papers, 2018 to 2025). A chronic inflammatory process causing damage and fibrosis of the pancreatic parenchyma. "miR-217 also directly targets SIRT1, it is inversely correlated to SIRT1 expression and is down-regulated in chronic pancreatitis and PC." (PMID 30319549, 2018). "However, SIRT1 has an opposing effect on chronic pancreatitis compared to AP." (PMID 36581622, 2022).
colon adenocarcinoma (5 papers, 2019 to 2025). "To determine how Sirt1-Tg CSMCs inhibited colonic epithelial regeneration following DSS-induced injury observed in the model, we used the conditioned media (CM) of WT and Sirt1-Tg CSMCs induced with TNF-α to treat human colon adenocarcinoma Caco-2 cells." (PMID 40076434, 2025). "Based on the transcriptome analysis results, the expression of SIRT1 was upregulated in colon adenocarcinoma samples." (PMID 37490168, 2023). "In addition, FOXD3-AS1 antagonizes the expression of miR-135a-5p and upregulates SIRT1 in colon adenocarcinoma HCT116 and SW1116 cells, thus contributing to cell invasion and migration." (PMID 35280790, 2022). "In colon adenocarcinoma, FOXD3-AS1 was found to protect HCT116 and SW1116 cells from apoptosis via the regulation of miR-135a-5p/SIRT1 axis." (PMID 35280790, 2022). "In colon adenocarcinoma, FOXD3-AS1 was shown to upregulate SIRT1 by clearing miR-135a-5p in HCT116 and SW1116 cells, which is suggestive of increased cell." (PMID 35280790, 2022).
Ewing sarcoma (5 papers, 2013 to 2025). A small round cell tumor that lacks morphologic, immunohistochemical, and electron microscopic evidence of neuroectodermal differentiation. "SRT1720, a first-generation synthetic SIRT1 activator, was reported to significantly enhance vincristine-induced Ewing's sarcoma cell death." (PMID 41170449, 2025). "In tumor specimens, previous a study have revealed the Notch signaling was inactivated due to SIRT1 overexpression in Ewing sarcoma cells and offered a novel treatment option in metastatic Ewing sarcoma." (PMID 25420528, 2014). "We tested the necessity of these three co-repressors in BCL11B-mediated repression in Ewing sarcoma cells by shRNA knock-down for chomodomain helicase DNA binding protein 4 (CHD4), the core component of the NuRD complex, or chemical inhibitors targeting SUV39H1 or SIRT1." (PMID 23527175, 2013).
gastric tumors (5 papers, 2015 to 2024). "Jaridon 6, for example, inhibits the PI3K/Akt/mTOR axis to induce autophagy and reduces SIRT1 expression, weakening drug resistance in gastric tumors." (PMID 39403142, 2024). "This miRNA also suppresses histone deacetylase SIRT1 in gastric tumor cells, increasing proliferation and tumor progression." (PMID 35645340, 2022). "High expression of SIRT1 protein helps maintain the malignant status of stomach tumors." (PMID 28061480, 2017). "Some studies found that SIRT1 might play a role in tumor cell metastasis, such as brain and gastric tumors." (PMID 26318035, 2015). "This supported the hypothesis that SIRT1 and STAT3 functioned independently in advanced tumors as important oncogenes to maintain the malignancy of stomach tumors resulting in poor survival outcomes in patients with high expression of both SIRT1 and STAT3." (PMID 28061480, 2017). "Therefore, we studied if SIRT1 and STAT3 collaborate during gastric tumor progression." (PMID 28061480, 2017).
gouty arthritis (5 papers, 2021 to 2025). "It has been demonstrated that its metabolite, resveratrol, inhibited MSU crystal-induced inflammation and suppressed the onset of gout in mice by acting, in particular, on SIRT1 expression, and consequently on the levels of PPARγ." (PMID 33805648, 2021). "Patients with gout have reduced levels of SIRT1, which might be, therefore, restored by resveratrol." (PMID 33805648, 2021). "Thus, activating Sirt1 may provide a new therapeutic target for gouty arthritis." (PMID 38739197, 2024). "Taken together, our data reveal that S14G-HNG protected against MSU crystals-induced gouty arthritis by regulating SIRT1, suggesting that S14G-HNG might be a promising therapeutic agent for the treatment of gouty arthritis." (PMID 34965184, 2022).
Hashimoto thyroiditis (5 papers, 2020 to 2023). An autoimmune disorder caused by the production of autoantibodies against thyroid tissue. "Interestingly, the expression was also decreased in Hashimoto’s thyroiditis patients, indicating decreased SIRT1 is a common phenomenon in autoimmune thyroiditis (AITD)." (PMID 32485674, 2020). "Th1 cytokines drive oxidative stress and cause a significant decrease in SIRT1 expression associated with HIF-1α, GLUT-1, and VEGF-A upregulation, suggesting that SIRT1 (a key regulator of oxidative stress) may be regarded as a potential therapeutic target for Hashimoto’s thyroiditis." (PMID 37483618, 2023). "Hashimoto’s thyroiditis is similar to Graves’ disease in that reduced FOXP3 expression levels, and defective Treg function are regulated by SIRT1-mediated aberrant FOXP3 acetylation in patients with Hashimoto’s thyroiditis." (PMID 37483618, 2023).
hyperhomocysteinemia (5 papers, 2019 to 2025). A serious metabolic condition caused by mutations in the MTHFR gene, medications, or nutritional deficiency. "MTX suppresses methionine generation, resulting in hyper-homocysteinemia, which causes cellular oxidation that reduces Sirt1/Nrf2 mediated glutathione production and induce tissue injury." (PMID 38831428, 2024). "Hyperhomocysteinemia (Hhcy) increases NOX activation through repressing SIRT1 and AMPK, inducing endothelial inflammation and apoptosis." (PMID 33658920, 2020). "The reduction of the SIRT1/AMPK/PGC-1α and PPAR-γ signaling pathways by the perturbed homocysteine expression caused deleterious effects on chondrocytes, indicating a possible correlation between hyperhomocysteinemia and OA." (PMID 37020714, 2023).
hyperphosphatemia (5 papers, 2018 to 2025). Abnormally high level of phosphate in the blood. "Mineral perturbations in CKD with resultant hyperphosphatemia have been shown to promote a systemic ageing phenotype by downregulating the expression of SIRT1." (PMID 39497615, 2025). "Further, hyperphosphatemia induces VC by osteogenic conversion, apoptosis, and senescence of VSMCs through the Pit-1 cotransporter, which can be retarded by the Sirt1 activator resveratrol." (PMID 32111067, 2020). "Therefore, Sirt1 is involved in hyperphosphatemia-related VC development, and rescue of Sirt1 expression is reasonable to inhibit cell senescence and osteogenic phenotype switching of VSMCs." (PMID 32111067, 2020). "In hyperphosphatemia-induced VC in CKD, resveratrol can significantly alleviate VSMC senescence and VC by activation of Sirt1." (PMID 32111067, 2020).
Hypoglycemia (5 papers, 2017 to 2024). A decreased concentration of glucose in the blood. "Hepatic deletion of Sirt1 leads to mild hypoglycemia, increased glucose tolerance, decreased hepatic glucose production, decreased serum cholesterol and increased hepatic content of free fatty acids and cholesterol, all of which can be reversed by Sirt1 overexpression." (PMID 28536529, 2017). "For example, SIRT1 promotes FOXO1 deacetylation and PPARs activation to stimulate gluconeogenesis and fatty acid oxidation, thus inhibiting lipogenesis in organisms under hypoglycemia stress." (PMID 32397268, 2020).
hypothyroidism (5 papers, 2022 to 2025). Abnormally low levels of thyroid hormone. "SIRT1 has an important regulatory function in host defenses following infection, and mimics the effects of hypothyroidism on cerebral malaria." (PMID 41263555, 2025). "Treatment of euthyroid mice with a SIRT1 activator lowers thyroid hormone levels and mimics the effect of hypothyroidism, suggesting the involvement of this metabolic enzyme in the control of viral load." (PMID 41263555, 2025). "The number of circulating leukocytes, lymphocytes, and neutrophils was also lower in infected euthyroid mice treated with the SIRT1 activator, again mimicking the effect of hypothyroidism." (PMID 41263555, 2025). "In conclusion, thymoquinone was found to limit the hypothyroidism-induced structural changes in the testes, mostly through the upregulation of SIRT1 expression." (PMID 36506574, 2022). "The similar effects of hypothyroidism and SRT1720 on VACV infection prompted us to examine whether the SIRT1 activator alters thyroid hormone levels." (PMID 41263555, 2025). "Reduced SIRT1 may be behind the negative impact of hypothyroidism on the testicular structure that was observed in this study." (PMID 36506574, 2022).
intracerebral hemorrhage (5 papers, 2017 to 2022). A cerebrovascular disorder characterized by bleeding into one or both cerebral hemispheres including the basal ganglia and the cerebral cortex. "Zhou and colleagues provide evidence that activation of Sirt1 promotes the recovery of mitochondrial protein function through increased mitochondrial biogenesis and reduced apoptosis after intracerebral hemorrhage via the PGC-1α mitochondrial pathway." (PMID 32570218, 2020). "However, it is not clear if SIRT1 has protective effects after intracerebral hemorrhage (ICH)-induced brain injury in rats." (PMID 29375306, 2017).
kidney stone (5 papers, 2019 to 2025). "Given the important role of SIRT1 gene in calcium metabolism, genetic polymorphisms of SIRT1 are considered potential impact factors for hypercalciuria, which leads to nephrolithiasis." (PMID 30714469, 2019). "In present study, the association between nephrolithiasis and the expression of SIRT1 was firstly explored based on the mouse model of CaOx crystal-induced renal injury." (PMID 30714469, 2019). "Considering that vessels and tubules under conditions of OS represent the origins of plaques, we proposed a potential association between SIRT1 and the pathogenesis of nephrolithiasis." (PMID 30714469, 2019). "Associations of one haplotype in SIRT1 region with kidney stone." (PMID 30714469, 2019). "In this study, 6 common non-coding SNPs of SIRT1 were selected as tags for analysis to explore the relationship between the SIRT1 gene and kidney stone formation." (PMID 30714469, 2019). "Further studies with larger sample sizes are required to explore the potential relationship between SIRT1 and nephrolithiasis." (PMID 30714469, 2019). "Reduced expression of SIRT1 was observed in the kidney of the mice in the crystal group, revealing the potential role of SIRT1 in the nephrolithiasis." (PMID 30714469, 2019). "In conclusion, the reduced expression of SIRT1 was observed in the injured kidney of the mice induced by CaOx crystal, revealing the potential role of SIRT1 in the nephrolithiasis." (PMID 30714469, 2019). "In this study, the role of SIRT1 gene in nephrolithiasis was firstly explored based on a mouse model of CaOx crystal-induced renal injury." (PMID 30714469, 2019). "The reduced expression of SIRT1 in the crystal group was both observed in the wild-type mice and the ApoE KO mice, revealing the potential role of SIRT1 in the nephrolithiasis." (PMID 30714469, 2019). "Therefore, SIRT1 is considered a new potential therapeutic target for kidney stones and warrants further investigation." (PMID 30714469, 2019). "Sirtuin 1 (SIRT1), an NAD+-dependent deacylase, has been identified to be associated with renal tubular inflammatory conditions and metabolic disorders, which are risk factors of nephrolithiasis." (PMID 30714469, 2019). "In addition, we genetically analyzed 6 SNPs of the SIRT1 gene in kidney stone patients and controls." (PMID 30714469, 2019). "Limited studies have indicated that kidney stones showed downregulated expression of SIRT3 and SIRT1." (PMID 36581622, 2022). "However, the correlation between SIRT1 polymorphisms and nephrolithiasis has not been studied." (PMID 30714469, 2019). "Therefore, we could focus on the effects of SIRT1 gene in nephrolithiasis locally." (PMID 30714469, 2019).
muscle atrophy (5 papers, 2019 to 2025). The loss of muscle tissue due to inactivity or disease. "Collectively, these findings demonstrate irisin alleviates glucocorticoid-induced muscle atrophy via SIRT1-dependent pathways, rebalancing muscle physiology and systemic energy homeostasis." (PMID 41227321, 2025). "Collectively, these in vivo findings confirm that R-irisin mitigates Dex-induced muscle atrophy and mitochondrial dysfunction through SIRT1-dependent pathways, reinforcing its therapeutic potential for sarcopenic disorders." (PMID 41227321, 2025). "SIRT1 overexpression is capable of reducing Atrogin1 and MuRF1 induction via FoxO transcription factors in other muscle atrophy models." (PMID 30992039, 2019).
neuropathic pain (5 papers, 2016 to 2023). Chronic pain caused by damage to nerve fibers. "As compared with healthy volunteers, neuropathic pain patients exhibited an increased expression of miR-124a (2.5 ± 0.7, P < 0.05) and miR-155 (1.3 ± 0.3; P < 0.05) and a reduced expression of SIRT1 (0.5 ± 0.2; P < 0.01)." (PMID 37928202, 2023). "As compared to healthy volunteers, neuropathic pain patients exhibited an increased expression of miR-124a (2.5 ± 0.7, p < 0.05) and miR-155 (1.3 ± 0.3; p < 0.05) as well as a reduced expression of SIRT1 (0.5 ± 0.2; p < 0.01)." (PMID 27646435, 2016). "This study explored for the first time the relationship between resveratrol-activated Sirt1 and the miR-182/Nav1.7 downstream target in the development of CCI–induced neuropathic pain." (PMID 32089065, 2020).
optic neuropathies (5 papers, 2017 to 2024). "SIRT1 prevents retinal ganglion cell (RGC) loss in models of optic neuropathy following pharmacologic activation or genetic overexpression." (PMID 33589779, 2021). "A multitude of data has implicated a role for SIRT1-induced mitochondrial biogenesis in RGC survival in ONC, inflammatory, and viral-induced optic neuropathies." (PMID 33589779, 2021). "Together, these results suggest that modulating SIRT1 can promote RGC survival in multiple forms of optic neuropathy." (PMID 33589779, 2021). "This study expands our understanding of SIRT1 mediated neuroprotection in the context of compressive or traumatic optic neuropathy, making it a strong therapeutic candidate for testing in all optic neuropathies." (PMID 33589779, 2021). "The mitochondrial biogenesis and RGC survival induced by SIRT1 in optic neuropathies makes it an excellent target gene for developing a gene therapy treatment." (PMID 33589779, 2021). "In conclusion, the study provides valuable insights into the mechanisms of SIRT1-mediated neuroprotection in the context of compressive or traumatic optic neuropathy, positioning it as a promising therapeutic candidate for further testing in various types of optic neuropathies." (PMID 39456800, 2024). "This study expands our understanding of SIRT1 and NRF2-mediated neuroprotection in the context of MS pathogenesis and optic neuropathies." (PMID 29494741, 2018).